CD47 (CD47 molecule)
Diseases named in the same sentence as CD47 in open-access papers (continued):
Sharing a sentence is not in itself a finding about the gene and the disease.
tumor (continued). "Nonetheless, CD47 remains a potential therapeutic target for improving the efficacy of anti-tumor Abs, provided that the therapy of choice selectively targets only CD47 on the target tumor cells." (PMID 39712032, 2024). "One approach trying to utilize macrophages for immunotherapy has been to block the CD47-SIRPα axis, which mediates inhibitory signaling, to promote phagocytosis of tumor cells." (PMID 39257438, 2024). "We utilized a well‐documented CD47 nanobody, which is reportedly ineffective as a monotherapy for tumor growth, for the combination therapy." (PMID 38888519, 2024). "Some studies have demonstrated that aCD47 can inhibit the interaction of CD47 and SIRPα to facilitate DC maturation and tumor cell phagocytosis by TAMs." (PMID 38560565, 2024). "Regarding a macrophage-mediated anti-tumor immunotherapy strategy based on gene-edited nanoparticles: the first step involves blocking the CD47-SIRPα pathway, and the second step is to repolarize tumor-associated macrophages." (PMID 38650924, 2024). "The cyclization of CD47 N-terminal pyroglutamate on the tumor cell surface can enhance its binding ability to SIRPα." (PMID 38429732, 2024). "During tumor progression, high density of tumor cells express CD47 and bind to the corresponding receptors on macrophages to evade the immune system." (PMID 39192984, 2024). "This suggests that engagement of myeloid cell SIRPα would be predominantly driven via interactions with other stromal components expressing CD47 in addition to those with tumor cells." (PMID 38577107, 2024). "In this retrospective study, formalin-fixed paraffine-embedded (FFPE) tumor tissues of 55 treatment-naïve patients were evaluated by immunohistochemistry for the abundance of CD47 molecule on tumor cells." (PMID 38493445, 2024). "Current research indicates that the inhibitory LILRB1 protein often features a common clone, GHI/75, which, when combined with anti-CD47 monoclonal antibodies, significantly boosts macrophages’ ability to engulf and kill tumor cells." (PMID 38273373, 2024). "In pancreatic ductal adenocarcinoma (PDAC), MLKL has been observed to enhance CD47-SIRPα signaling in tumor cells, which in turn inhibits macrophage phagocytosis and enables tumor cells to evade immune clearance." (PMID 39575419, 2024). "The use of these agents that inhibit the CD47-SIRPα cancer signaling pathway has been shown to lead to the phagocytosis and elimination of the tumor cells." (PMID 39795582, 2024). "Tumor cells can further evade immune surveillance by upregulating the CD47 “don’t eat me” signal, a defensive mechanism that discourages phagocytosis." (PMID 38217016, 2024). "Excessive activation of pyroglutamate cyclase is a key factor leading to tumor evasion of macrophages via the CD47-SIRPα signaling pathway." (PMID 38429732, 2024). "6MW3211 efficiently disrupted PD-1/DP-L1 and CD47/SIRPα signaling and demonstrated potent therapeutic effects in three tumor models." (PMID 39588148, 2024). "Specifically, there is a gap in comprehending the influence of CD47 on the tumor immune microenvironment, particularly in relation to CD8 + T cells." (PMID 38720108, 2024). "Rapid development of checkpoint inhibitors has provided significant breakthroughs for cancer stem cell (CSC) therapy, while the therapeutic efficacy is restricted by hypoxia-mediated tumor immune evasion, especially hypoxia-induced CD47 overexpression in CSCs." (PMID 38699238, 2024). "The frequency of CD47+ tumor cells was significantly higher in spheroids from MA than in tumoroids from tumor tissue." (PMID 37876933, 2023). "The overexpression of CD47 has been identified in many tumors, and its level positively correlates with tumor evasion and metastasis." (PMID 36823373, 2023). "In this study, we designed PD‐1/SIRPα fusion HAC NVs, which dual‐target the highly expressed immune checkpoint proteins PD‐L1 and CD47 on tumour cells." (PMID 37974395, 2023).
tumor (continued). "CD47 on the tumor surface produces corresponding signals by binding to SIRPα on macrophages, which makes macrophages unable to recognize and phagocytize tumor cells." (PMID 37171006, 2023). "Preclinical studies have demonstrated that blocking CD47 can enhance the efficacy of immunotherapy by enhancing immune cell infiltration and inducing tumor cell death." (PMID 38188674, 2023). "While CD47/SIRPα-axis inhibitors in combination with IgA therapy have shown promise, complete tumor eradication remains a challenge, indicating the presence of other checkpoints." (PMID 37444515, 2023). "CD47 is also up-regulated by hypoxia on tumor cells, thus resulting in the inhibition of tumor cells’ phagocytosis." (PMID 37443821, 2023). "Dysregulation of immune signaling molecules induced by multiple signaling pathways regulated by MYC, including CTLA-4, CD47, and PD-L1, can help tumor cells directly or indirectly escape the immune response." (PMID 36966168, 2023). "Below, we focus on inhibitory checkpoints regulated by PD-1/PD-L1, CTLA-4, and CD47 that suppress innate and adaptive immune cells including APCs and effector T cells that orchestrate tumor immunity." (PMID 37958404, 2023). "In vitro phagocytosis of tumor cells expressing miR-30a-3p or miR-30e-3p by macrophages was significantly enhanced after CD47/SIRPα blockade." (PMID 37446353, 2023). "Monocytes expressing SIRPalpha can phagocyte tumor cells with low levels of CD47 on their surface; the interaction CD47-SIRPalpha protects normal cells from this fate." (PMID 36768201, 2023). "There are multifactorial potential interactions between T-ALL and stroma that shape the myeloid anti-tumor immune response, including between CD47/SIRPα, PD-L1/PD-1, CD40/CD40L, and CD28/CD80/86." (PMID 36897988, 2023). "Human lymphoid tumor, bladder cancer, and breast cancer preclinical models show that anti-CD47 antibody treatment promotes adaptive immunity and exerts anti-tumor effects via CD8+T cells and dendritic cells." (PMID 37138860, 2023). "Our findings suggest a link between CD47, tumor immune response, and blood vessel invasion (CD31 positive)." (PMID 36598153, 2023). "Tumor cells heavily rely on the expression of ‘don’t eat me’ signals, which encompass molecules such as CD47, programmed cell death 1 ligand 1, β2-microglobulin, and other yet unidentified ligands." (PMID 37763721, 2023). "Emerging new data demonstrates that hypoxia is involved in the alteration of tumor metabolism and metabolites, pH regulation, and overexpression of several immune checkpoints including macrophage immune checkpoints CD47, PD-L1, and HLA-G." (PMID 37443821, 2023). "The inhibition of CD47 signaling can incite macrophage phagocytic activity, culminating in impaired tumor growth, the suppression of metastatic spread, and even tumor regression." (PMID 37822610, 2023). "More importantly, anti-CD47 antibodies were found to inhibit in vivo tumor growth and exerted a synergistic effect with 5-Fu treatment." (PMID 36860925, 2023). "For instance, combination therapies incorporating CD47 blockade and checkpoint inhibitors have exhibited improved anti-tumor immunity and enhanced tumor regression." (PMID 38188674, 2023). "Magrolimab is a monoclonal antibody that targets the CD47 surface marker of tumor cells, also known as the “don’t eat me” signal, promoting their phagocytosis by macrophages." (PMID 36902450, 2023). "CD47 is a transmembrane protein expressed at a basal level in many cell types but is often overexpressed in tumor cells." (PMID 37373873, 2023). "Compared with conventional CD47 antibodies, the use of Lemzoparlimab effectively targets tumor cells while minimizing the adverse erythrocyte effects, thereby avoiding severe anemia." (PMID 37484024, 2023). "Briefly, 200 μg/mL NVs or 20 μg/mL Atezolizumab and Magrolimab were thoroughly mixed with 1 × 106 MDA‐MB‐231 cells for 30 min to bind PD‐L1 and CD47 expressed on tumour cells." (PMID 37974395, 2023).
tumor (continued). "This first-in-class compound is a cyclic pentapeptide that has been demonstrated to reprogram myeloid-derived suppressor cells (MDSCs) to produce TSP-1 in the TME, which can then bind to CD36 and CD47 on tumor and endothelial cells." (PMID 37371076, 2023). "We examined the potential antitumor action of an antibody to human SIRPα (SE12C3) that inhibits the interaction of CD47 on tumor cells with SIRPα on human macrophages and thereby promotes Fcγ receptor–mediated phagocytosis of the former cells by the latter." (PMID 38162643, 2023). "Recently, several groups reported some SIRPα mutants and CD47 antibodies showed different binding ability to CD47 on tumor cells and normal cells, indicating different glycosylation model on CD47 in malignancy and normal cells." (PMID 36593962, 2023). "For instance, anti-CD47 antibody or CD47 fusion protein can block the signal transduction in this pathway, thus enhancing the recruitment of macrophages to tumor tissues and leading to increased the immune clearance ability of macrophages to tumor cells." (PMID 37484024, 2023). "CD47 is a “self-labeling molecule” expressed on nearly all normal cells and overexpressed on most tumor cells." (PMID 37049910, 2023). "It has been shown that the phagocytosis of macrophages within the tumor microenvironment can be enhanced when the binding of CD47 and SIRPα was blocked." (PMID 37049910, 2023). "CRC-bearing Jax mice responded to anti-CD47 immunotherapy, while tumor-bearing Tac mice exhibited low responsiveness to CD47 blockade." (PMID 37868956, 2023). "SIRPa-exosomes, acting as immune checkpoint blockade, antagonizes the crosstalk between CD47 and SIRPa, and induce tumor phagocytosis." (PMID 37064113, 2023). "It is therefore highly notable that the antibodies examined in these studies only target tumor cells expressing human CD47 in these models." (PMID 36650558, 2023). "As an important protein complex in the tumor immune response, CD47-SIRPα has great potential in the field of drug developments." (PMID 37375166, 2023). "CD47 is a membrane-bound protein that is highly expressed on tumor cells and binds to signal regulatory protein α (SIRPα) on macrophages, delivering a “don't eat me” signal that leads to immune evasion by the tumor." (PMID 37993941, 2023). "Anti-CD47 Ab in combination with doxorubicin exerts maximal effects on tumour suppression in a patient-derived HCC xenograft mouse model, as compared to monotherapies alone." (PMID 37894344, 2023). "To clarify the tumor expression of Cd24 and Cd47 in human GCTs, we performed q-PCR on KGN cell line, which originated from a Stage III granulosa cell carcinoma." (PMID 36823373, 2023). "Evidence suggests that CD47 is a dominant anti‐engulfment signal on tumor cells and is overexpressed in various cancers." (PMID 36598153, 2023). "Formerly known as hu5F9-G4, magrolimab has been demonstrated to bind to CD47 and facilitate efficient macrophage-mediated phagocytosis of tumor cells." (PMID 37345054, 2023). "For example, blockade of the phagocytosis checkpoint SIRPA, which binds to CD47 that is upregulated on tumor cells, has been shown to enhance myeloid cell-dependent killing of Burkitt’s lymphoma through antibody-dependent cellular phagocytosis in SRG mice." (PMID 37296949, 2023). "CD47 antibodies have been utilized to block CD47 and promote phagocytic clearance of tumor cells in various preclinical studies." (PMID 36823443, 2023). "In our research, we took the modified gcForest into realistic application to screen the new compounds for an anti-tumor immune target, cluster of differentiation 47 (CD47)." (PMID 37927570, 2023). "TSP1 has multiple activities in the tumor microenvironment that modulate tumor growth and metastasis via CD47-dependent and -independent mechanisms." (PMID 36768931, 2023). "CD47-mediated signaling plays a critical role in regulating tumor growth and progression by facilitating communication between cancer cells and stromal cells in the TME." (PMID 38188674, 2023).
tumor (continued). "Whilst CD47 blockade by constitutively secreted anti-CD47 scFv also blocked anti-macrophage phagocytosis of tumor cells and diminished polarization of macrophages to the inhibitory phenotype, which significantly ameliorated TME." (PMID 37781520, 2023). "Strategies include manipulation of the antibody structure or increasing specificity with a bispecific molecule target CD47 and a tumor antigen." (PMID 37090720, 2023). "In vivo and ex vivo imaging further demonstrated the tumor‐targeting ability of anti‐CD47‐PCM@NP, with enhanced tumor accumulation of both the antibody and the nanoparticle." (PMID 36683161, 2023). "The results of these studies indicated that the mechanisms of action of these tumor-opsonizing mAbs can be greatly potentiated by anti-CD47 strategies." (PMID 38033495, 2023). "The anti-PD-L1 arm is high affinity to PD-L1 expressing on tumor cells, and the anti-CD47 arm is low affinity to reduce the potential cytotoxicity even in high concentration." (PMID 36593962, 2023). "Our present data support for the first time the use of a PI3Kδ inhibitor to promote the remodeling of the tumor microenvironment in vitro and in vivo, for a better anti-CD47-mediated activation of macrophages." (PMID 37153563, 2023). "An adenovirus-based tumor vaccine loaded with a CD47-targeting nanobody fused with the IgG2a Fc protein was found to induce anti-tumoral immunity and promote tumor regression and overall long-term survival in mice." (PMID 37626741, 2023). "We showed that CD8+ T cells infiltration significantly increased in the tumor microenvironment of mice receiving anti-CD47 as one of their treatment regimens." (PMID 36774400, 2023). "A pro-phagocytic signal of CALR is counteracted by CD47, and blockage of CD47 is reported to induce in vivo tumor elimination by stimulating phagocytosis of cancer cells." (PMID 36943734, 2023). "Overexpression of CD47 is frequently observed in various types of human malignancies, inhibiting myeloid-mediated elimination of tumor cells and affecting the prognosis of cancer patients." (PMID 36939440, 2023). "Our findings here show the promising value of blocking the CD47/SIRPα axis to replenish immune mobilization in the tumor microenvironment, which is of clinical benefit for improving the low treatment response rate of CRC." (PMID 36626230, 2023). "KWAR23, a SIRP α monoclonal antibody which blocks its binding to CD47, enhances myeloid cell-dependent tumor killing ability, activates neutrophils and macrophages, and inhibits tumor growth." (PMID 37064113, 2023). "In summary, CD47 can play different functional roles in tumour or immune cells by binding to SIRPα on the cell surface or to the secreted TSP1 protein." (PMID 38037074, 2023). "Our further studies showed that GCTs are derived from single mutant GCs that escape immune surveillance by expressing higher levels of Cd47 and Cd24a, while blocking CD47 in mice bearing GCTs efficiently decreases tumor size." (PMID 36823373, 2023). "Of 282 cases, 93 (33%) showed high CD47 tumor cell expression, and high counts of CD68 TAMs were found in 68 cases (24%)." (PMID 36598153, 2023). "CD47 blockade synergizes with cytotoxic therapies that stress tumor cells and induce immunogenic cell death." (PMID 37468567, 2023). "In contrast, CD47 K99/102R expression, which increased CD47 expression in tumors, accelerated tumor growth and shortened mouse survival time." (PMID 37541303, 2023). "According to this theory, our team generated several tumor CD47 specific antibodies by using tumor cells and RBCs for FACS counter screening." (PMID 36593962, 2023). "Blocking CD47 decreases tumor burden in vivo and in vitro, as demonstrated by numerous models and clinical investigations." (PMID 37719086, 2023).
tumor (continued). "By this, HX009 blocks the binding of CD47 on tumor cells with SIRPα on macrophages and DCs and, therefore, activates macrophage-mediated phagocytosis of the CD47-expressing tumor cells." (PMID 36900399, 2023). "Both Cd24 and Cd47 were detected in KGN cells, suggesting the Cd24 and Cd47 were expressed in tumor cells of human GCTs." (PMID 36823373, 2023). "CD47, a receptor of signal regulatory protein α (SIRPα), is one of the “don’t eat me” signals expressed on healthy cells and frequently over-expressed on tumor cells." (PMID 37345054, 2023). "TSP-1, the binding protein of CD47, restricts antitumor immunity via CD47-dependent regulation of innate and adaptive immune cells by regulating angiogenesis and perfusion of the tumor vasculature." (PMID 36882399, 2023). "Binding of CD47 to the SIRPα receptor expressed on APCs transmits a “don’t eat me” signal to prevent tumor cell engulfment by phagocytes." (PMID 37958404, 2023). "The principle basis for testing biologicals targeting human CD47 using xenograft tumor models revolves around the fact that the polymorphic SIRPα in NOD mice interacts with human CD47, supporting the growth of xenografts." (PMID 37012357, 2023). "After intravenous administration, nanobiological conjugates were actively concentrated in the tumor through the specific recognition of aCD47 and CD47 on the surface of tumor cells." (PMID 37457707, 2023). "CD47 is a transmembrane protein that is ubiquitously expressed on the surface of multiple types of cells, including tumours and diverse immune cells." (PMID 38037074, 2023). "The CD47-SIRPα pathway on tumor cells prevents phagocytosis by binding to macrophage SIRPα, serving as a “do not eat me” signal." (PMID 38258072, 2023). "Tumor cell escape macrophage-mediated phagocytosis via increasing the CD47 expression, which recognizes signal regulatory protein-α (SIRPα, a phagocytosis inhibitory receptor)." (PMID 37380989, 2023). "Exploiting this physiological checkpoint, tumor cells often upregulate CD47 and thereby escape recognition and removal by macrophages." (PMID 38164132, 2023). "High expression of CPT1A not only enhances radiotherapy resistance in GBM tumor cells, but also enhances immune escape of macrophages through CD47, suggesting CPT1A as a novel strategy for the treatment of recurrent GBM multiforme." (PMID 37033619, 2023). "Overactivation of MYC in adaptive immune cell subsets mainly reduces the killing effect on the tumor by inhibiting effector T cells, in which MYC regulates the expression of CD47 and PD-L1 in various types of tumor cells." (PMID 36966168, 2023). "Targeting CD47 alone has been efficacious in several preclinical tumor models 30; however, combination strategies offer increased therapeutic potential." (PMID 36860925, 2023). "Compared with ferritin nanocages, signal regulatory protein α (an antagonist of CD47 on tumor cells) expressed on EVMs is more conducive to the spatial arrangement of binding with CD47 on the surface of tumor cells." (PMID 37242738, 2023). "Whereas targeting the CD47-SIRPα interaction restores phagocytic activities, the strategy is sometimes suboptimal due to the possibility that tumor cells exploit the reverse signaling mechanism for survival." (PMID 37848444, 2023). "Blocking the mutual recognition between CD47-SIRPα or CD24-Siglec10 using large molecular proteins or small molecular drugs represents a promising avenue for tumor immunotherapy." (PMID 37484024, 2023). "This increase in MDSC per gram of tumor was reversed by using anti-CD47 in consistent with its effect on Treg content in the tumor." (PMID 36774400, 2023). "At present, the research and development of drugs that target the “do not eat me” signaling pathway is a hot topic in the new generation of tumor immunotherapy, with drugs that focus on the CD47-SIRPα axis show rapid progress in clinical development." (PMID 37484024, 2023).